LEP (leptin)
Diseases named in the same sentence as LEP in open-access papers (continued):
Sharing a sentence is not in itself a finding about the gene and the disease.
Obesity (continued). "The interest in BAT in inflammation and obesity is supported by proteomics analysis, which also provided data on some cytokines expressed by BAT (frontiers), including leptin, adiponectin, and IL6." (PMID 39770044, 2024). "Overall, the levels of leptin, adiponectin, and GGT were significantly higher in children with obesity." (PMID 39771030, 2024). "Thus, impaired adiponectin and leptin signaling may contribute to the negative effects of obesity on the CNS and increase the risk of cognitive decline and AD." (PMID 39273520, 2024). "Similarly, are individuals with obesity with modest hyperleptinemia a subgroup that might be responsive to leptin therapy, with appetite suppression and reduction in fat mass in response to exogenous leptin ?" (PMID 38165042, 2024). "This analysis showed that some proteins, such as COL1A1, COL6A3, FABP4, LEP, LGALS1, and THBS4, are obesity-specific, and GDF15, LPL, MCFD2, REG1A, REG1B, and TCN2 are T2D-specific." (PMID 38732002, 2024). "Leptin (LEP) and adiponectin (ADPN) are two adipocytokines that have been widely studied in connection with obesity." (PMID 39194505, 2024). "Other studies reported a positive correlation between leptin and PAI-1 serum levels in obesity and metabolic syndrome." (PMID 39062875, 2024). "There are also reports indicating inhibition of leptin signaling in the hypothalamus by PTP1B and Tyrosine Phosphatase of T cells (TCPTP), contributing to obesity." (PMID 39057043, 2024). "Here, we find that obesity decreases DNA hydroxymethylation and TET2 levels in adipocytes via the leptin signaling pathway." (PMID 38561362, 2024). "Therefore, elevated leptin levels could increase the risk of the subsequent development of obesity-related non-communicable diseases such as CVD, type 2 diabetes, metabolic syndrome (MetS), and even some types of cancer." (PMID 38668349, 2024). "The interaction between leptin and VEGF in obesity-induced ASM remodeling should be considered, as higher levels of serum VEGF were observed in individuals with obesity compared to the control group." (PMID 38562155, 2024). "Obesity’s mechanical effects may also contribute to esophageal disease and other GI symptoms, while a recent study found that adipocyte-secreted peptides such as leptin, adiponectin, nesfatin-1, and apelin can affect GI motility by acting both centrally and peripherally." (PMID 38397726, 2024). "Additionally, trodusquemine (MSI‐1436), an investigational drug, has been shown to combat obesity and metabolic disorders by inhibiting the enzyme protein tyrosine phosphatase 1b (Ptp1b), consequently reducing hepatic lipogenesis and counteracting insulin and leptin resistance." (PMID 38798180, 2024). "The impact of obesity and OSAS on plasma leptin levels is up to now controversially discussed in the literature." (PMID 38172514, 2024). "Regarding CLOCK/CT, FTO/AT, GHRL/GT, LEP/GA, LEPR/AG, MC4R/CT we found intermediates values for weight, BMI, waist circumference, and WHR, reflecting moderate levels of body fat and obesity." (PMID 39203789, 2024). "PD-1 expression in these macrophages is induced by obesity-related factors, including IFNγ, TNF, leptin, insulin and palmitate." (PMID 39402302, 2024). "We calculated the Hardy-Weinberg Equilibrium (HWE) for six genes (CLOCK, GHRL, FTO, LEP, LEPR, MC4R) related to obesity, using genotype frequencies from our dataset." (PMID 39203789, 2024). "It is important to stress that this leptin resistance in DIO mice is only partial, as obesity in these mice is much less severe than obesity in db/db mice completely lacking leptin receptor." (PMID 38165042, 2024). "Therefore, the approach to treating obesity by targeting leptin may require appropriate adjustment." (PMID 39872218, 2024).
Obesity (continued). "The study investigated the effects of various extracts on plasma levels of leptin, insulin, triiodothyronine (T3), thyroxine (T4), triglycerides, high-density lipoprotein (HDL), low-density lipoprotein (LDL) and lipase enzyme in obesity-induced rats." (PMID 39055496, 2024). "To characterise the role of leptin in the modulation of NLRP3 inflammasome profile changes and subsequent macrophage activation in the ovary during obesity, we used two genetically obese db/db and ob/ob mice, DIO mice, and the leptin treated LEPT mice." (PMID 38580672, 2024). "These share a common root cause, and, therefore, explain why we see leptin and insulin rising where obesity may not, or may rise later on, meaning that obesity was not the first mover in causing the rises in these biomarkers associated with chronic metabolic diseases." (PMID 39062126, 2024). "Against this background, the expression of key pro‐inflammatory factors, Leptin and TNF‐α and anti‐inflammatory proteins namely PPARγ and adiponectin in the adipose can be manipulated in favour of obesity reduction." (PMID 39698791, 2024). "In contrast, in WAT dysfunction in obesity, pro-atherogenic factors, such as FFAs, TNF-α, IL-6, resistin, and leptin, are secreted, which increase the development of atherosclerosis, internal plaque inflammation, and plaque vulnerability." (PMID 38051471, 2024). "Leptin serum levels are increased in OSA syndrome patients, mostly because of obesity, and, in some studies, it correlated with the severity of this syndrome." (PMID 37048738, 2023). "During obesity, high serum leptin levels develop resistance to leptin in the BBB transporter which leads to a decrease in leptin reaching the brain." (PMID 37372025, 2023). "There are significant differences in body composition as well as concentrations and function of adipokines, such as leptin, adiponectin, and FGF21, between pregnant women with a history of RYGB, women with obesity, and normal-weight controls." (PMID 37299461, 2023). "On the other hand, this transcription factor has been found to regulate the expression of obesity-related bioactive molecules (i.e., IL-6, IGF-1, and leptin), further suggesting the potential role of CEBP-β in mediating BC cell/adipocyte crosstalk." (PMID 37447165, 2023). "At the same time, however, it is known how dysregulation of this pathway can result in metabolic conditions and obesity; just think of the hyperactivation of JAK-STAT3-SOCS in the setting of leptin resistance." (PMID 37701031, 2023). "Again, negative modulation of osteoblast differentiation by leptin during obesity was mediated by activation of the JAK/STAT pathway, which was also involved in the leptin-mediated promotion of osteogenesis under normal conditions." (PMID 36750692, 2023). "During the research overview it was found that white and brown adipose tissue communicate with skeletal muscles and the heart through the secretion of leptin (LEP) and omentin (OMEN) whose concentrations significantly alter with the development of obesity." (PMID 37109160, 2023). "Future studies measuring the levels of sex hormones and body fat compositions along with ANGPTL8 levels in adolescents are required to validate the observed relationships that ANGPTL8, chemerin, leptin, and CRP have with obesity." (PMID 38189043, 2023). "As expected, in regard with previous results, we found higher levels of leptin and hs-CRP in subjects with obesity than subjects with overweight." (PMID 37081489, 2023). "The specific influence of obesity and OSAS on individual plasma leptin levels is controversially discussed." (PMID 36921085, 2023). "Subjects with obesity showed significantly higher values of NOV/CCN3, leptin and FGF21, and significantly lower values of adiponectin than normal-weight subjects." (PMID 38137540, 2023).
Obesity (continued). "Consequently, changes in the leptin-NPY axis may occur in obesity, but paradoxically, the vast majority of obese individuals do not have reduced but higher circulating leptin concentrations that do not lead to a reduction in appetite, indicating leptin resistance." (PMID 38260166, 2023). "Short-term high-intensity interval running (90% HRmax, 7 sessions) had a greater impact than MICT in decreasing the leptin levels and the IFN-γ expression in males with obesity (mean age 28.5 years)." (PMID 37608837, 2023). "The group of children with obesity who decreased their SDS-BMI after 9 months presented a decrease in the levels of liver enzymes, leptin, markers of IR, inflammation and endothelial dysfunction, and variables associated with MetS." (PMID 36894963, 2023). "Further evidence supports the role of obesity-induced inflammatory responses (IL-6, TNF-α, and leptin) in tamoxifen-acquired BC resistance." (PMID 36880535, 2023). "We then assessed the proportion of the effect of obesity on VTE, DVT, and PE explained by circulating leptin levels." (PMID 37056282, 2023). "We assessed adiponectin, leptin, and GLP-1 to investigate the effects of different set structures on obesity-related biomarker in middle-aged women with obesity." (PMID 37176576, 2023). "Treatment with 17β-estradiol, leptin, IL-6, and TNF-α (ELIT) for obesity-related inflammation also decrease mitochondrial function and increase oxidative stress, aggressiveness, and motility in cell lines with low estrogen receptor beta (ERβ) expression." (PMID 36880535, 2023). "We have used our diet-induced obesity (DIO) mouse model of SDB and have shown that intranasal (IN) leptin treats OIRD in DIO male mice, decreasing the number of apneas and increasing minute ventilation without decreasing analgesia." (PMID 38162827, 2023). "Leptin and TNF-α are positively correlated with body obesity and contribute to promoting inflammation and IR development." (PMID 36991247, 2023). "There is still a lack of data concerning the impact of indole derivatives on the modulation of adiponectin, leptin, resistin and PAI-1 production in adipose tissue during obesity." (PMID 38136564, 2023). "The link between leptin and CD14 has also been supported by others that found leptin induces CD14/TLR4 activation by the JAK2-STAT3 signaling pathway to promote obesity-related osteoarthritis." (PMID 37447395, 2023). "It has also been shown that SOCS3 knockout mice had improved leptin sensitivity through increased hypothalamic STAT3 phosphorylation and POMC induction, while showing resistance to high-fat diet-induced obesity." (PMID 37571301, 2023). "Several studies suggest that in obesity, PVAT loses its anti-contractile activity or even promotes endothelial dysfunction along with an increase in leptin levels." (PMID 37190105, 2023). "Regarding inflammatory markers, the group with obesity had significantly higher total leukocytes (p < 0.005), ESR (p < 0.001), and leptin (p < 0.01) and lower total adiponectin and A/L ratio (p < 0.05) compared with the healthy participants." (PMID 37215211, 2023). "In obesity, various adipocyte-derived pro-inflammatory cytokines, including TNF-α, interleukin-1β, interleukin-6, monocyte chemotactic protein-1, leptin, and resistin are overproduced, contributing to IR." (PMID 37503477, 2023). "Gene expression of leptin, PAI-1, and tumor necrosis factor-α was lower in ABD than FEM SAT and higher in women with obesity than normal weight." (PMID 37455922, 2023). "Therefore, we suggest that, besides TNF-α, there should be other factors in the group with obesity involved in insulin resistance, like high levels of leptin, along with low levels of adiponectin and IL-10, which may interfere with inflammation control and insulin sensitivity." (PMID 37215211, 2023).
Obesity (continued). "Hyperinsulinaemia, leptin, aromatase activation and 17-β-oestradiol synthesis in WAT CLS drive the increased incidence of oestrogen-sensitive cancers in women with obesity (postmenopausal breast cancer, endometrial cancer, ovarian, thyroid cancer)." (PMID 37233716, 2023). "The condition of leptin resistance, observed in both obese animals and humans, can also attenuate cellular insulin sensitivity, and, in turn, insulin resistance can impair leptin signaling, thus leading to the frequent co-existence of T2DM and obesity." (PMID 37298571, 2023). "It modulates obesity markers such as glucose, INS, leptin, adiponectin, lipid profile, and liver enzymes." (PMID 37534085, 2023). "Also, inadequate sleep duration might affect ghrelin and leptin level; this may lead to increased appetite and consequently obesity, impaired glycemic control, higher levels of cortisol, changes in growth hormone concentration, coronary artery calcification, and higher risk of atherosclerosis." (PMID 36806201, 2023). "We evaluated biochemical and hormonal parameters of bone mineral metabolism, including leptin and NPY, as well as bone histomorphometry, in an experimental model of high-fat diet (HFD)-induced obesity in rats before and after rWAT Dnx." (PMID 37630764, 2023). "Finally, with regard to adipokines and inflammation parameters, interleukin-6 (IL-6) and leptin levels were significantly higher in patients with obesity than in normal-weight subjects, whereas adiponectin levels were significantly lower in individuals with obesity." (PMID 36833305, 2023). "Few studies have investigated the effects of resistance training with different set structures on BDNF, NGF, adiponectin, leptin, and GLP-1 blood levels in middle-aged women with obesity." (PMID 37176576, 2023). "Leptin administration stimulates the activity of PDE3B in the hypothalamus, leading to a reduction in cAMP concentration, which mediates leptin’s anti-obesity effect." (PMID 38027481, 2023). "Obesity renders ArcN NPY and POMC neurons resistant to leptin, including those that influence PVN TRH neurons." (PMID 36769012, 2023). "In obesity, levels of HDL-C are low due to increased leptin, increased CETP production, decreased adiponectin, increased HDL-C clearance by hepatic and endothelial lipase, and reduced cholesterol efflux to HDL-C in adipocytes." (PMID 38004588, 2023). "Leptin activation of Ob-R, STAT3 and induction of Yamanaka pluripotency transcription factors OCT4 and SOX2 are thought to be involved in obesity-related tumour growth." (PMID 37233716, 2023). "Leptin levels, elevated pre-pubertally in the children with overweightness/obesity as well as in children with ASD and normal BMI, decrease with age, in contrast to the increasing leptin levels in healthy controls." (PMID 36902307, 2023). "In concordance with studies of others, more pronounced HFD-induced obesity was observed in APP/PS1 mice, followed by increased amounts of the eWAT, resulting in elevated levels of plasma leptin, cholesterol, and TGs in 6- and 10-month-old mice." (PMID 37686722, 2023). "Therefore, in line with the results of these recent studies, it is believed that the adiponectin/leptin ratio may be an important inflammatory marker that can be used to investigate comorbidities in patients with severe obesity and MetS before and after bariatric surgery." (PMID 37571250, 2023). "The levels of LEP and ADPN were closely related to the obesity degree, and an increase in adipose tissue often lead to an increase in LEP levels and a decrease in ADPN levels." (PMID 37686768, 2023). "To conclude, the adipokines adiponectin, leptin, resistin, IL-6, MCP-1 and PAI-1 produced by the adipose tissue are deregulated in the context of obesity." (PMID 38136564, 2023). "Obesity and T2DM are accompanied by elevated levels of leptin and characterized by leptin resistance induced by hyperleptinemia." (PMID 37920605, 2023).
Obesity (continued). "Pregnant women with obesity and diabetes often have an increase in pro-inflammatory cytokines and adipokines, such as TNF-α, IL-6, IL-1β, leptin, and resistin, which are involved in the inflammatory response." (PMID 37515062, 2023). "Further, loganin inhibited metabolic abnormalities, such as hepatic steatosis and adipocyte enlargement, and increased the serum levels of leptin and insulin in both OVX- and HFD-induced obesity models." (PMID 36902181, 2023). "Increased circulating pro-inflammatory cytokines and adipokines (e.g. TNF-α, leptin, resistin, plasminogen activator inhibitor-1, CRP, IL-1β and IL-6) contribute to systemic inflammation in obesity but are also established predictors of cognitive impairment." (PMID 37086380, 2023). "These so-called ELKO mice were partially protected from obesity and exhibited a moderately improved metabolic phenotype in response to HFD despite elevated blood leptin levels." (PMID 37217565, 2023). "Results show that subjects with FPLD2 had significantly lower leptin and adiponectin levels and higher MCP-1 levels in comparison with subjects with obesity, despite similar metabolic complications." (PMID 37081489, 2023). "Similarly, adiponectin/leptin ratio values also showed a high negative correlation with several low-grade chronic inflammation markers; they have emerged as an important predictive marker of cardiometabolic risk associated with obesity and MetS." (PMID 37571250, 2023). "Leptin analogs and MC4R agonists are exclusively used for patients with obesity secondary to congenital/acquired generalized lipodystrophy and POMC deficiency, respectively." (PMID 37937009, 2023). "In addition to being good markers of adipose tissue-associated inflammation, both leptin and adiponectin are involved in the regulation of lipolysis, and thus reductions in adiponectin/leptin ratios may also reflect changes in this process, further metabolically contributing to obesity." (PMID 37571250, 2023). "The studies also showed decrease in responsiveness to leptin and insulin by these neurons upon chronic feeding of a high-fat diet (HFD), resulting in type-2 diabetes (T2D) and HFD-induced obesity." (PMID 36899905, 2023). "An interesting finding was that obese mice that were leptin-deficient showed better survival of skin grafts, which indicated that the transplant outcome observed in obese patients may not be directly related to obesity but to hyperleptinemia." (PMID 36873891, 2023). "The Janus protein tyrosine kinase (JAK)/STAT pathway, is a vital downstream mediator for diverse cytokines (IL-6), hormones (leptin) and growth factors (EGF), and is dysregulated in the context of obesity and metabolic disease, including HCC." (PMID 37361533, 2023). "During obesity, the inflamed VAT is a source of pro-inflammatory adipokines including tumour necrosis factor (TNF)-α, IL-6, IL-8, CRP, or leptin, among others, that are released into the circulation promoting systemic inflammation." (PMID 36831381, 2023). "In this manner, changes in leptin and visfatin expression and peptide content in the liver of subjects with a higher BMI observed in the current study might constitute a possible mechanism participating in fatty degeneration of the liver in overweight and obesity." (PMID 35549673, 2022). "In the context of the obesity-related breast TME, the leptin-Signal transducer and activator of transcription 3 (STAT3) axis promotes FAO and inhibits glycolysis of CD8+ Teff cells." (PMID 39872079, 2022). "Thus, we can speculate that the obesity hormone leptin sustains metabolism in breast cancer cells either directly, as previous reported, or indirectly, inducing the release from breast cancer cells of a large amount of small EVs bearing a specific protein cargo of mitochondrial components." (PMID 36361728, 2022).